EED (embryonic ectoderm development)
Diseases named in the same sentence as EED in open-access papers (continued):
Sharing a sentence is not in itself a finding about the gene and the disease.
overgrowth syndrome (4 papers, 2021 to 2025). A group of syndromes caused by genetic birth defects that may lead to the development of malignancies. "EZH2, EED, and SUZ12 are components of the polycomb repressive complex 2 (PRC2), and this likely explains why genetic changes in these genes cause similar overgrowth syndromes." (PMID 36927955, 2023).
colon cancer (3 papers, 2016 to 2023). "The importance of DCAF1 with respect to the observed interaction was further confirmed by the finding that DCAF1 knockdown almost completely abrogates the ability of EZH2 to interact with EED and SUZ12 in colon cancer cells." (PMID 37069142, 2023).
colorectal cancer (3 papers, 2018 to 2025). A primary or metastatic malignant neoplasm that affects the colon or rectum. "As we expected, RIP results revealed that SNHG1 bound with EZH2, SUZ12 and EED in colorectal cancer cells." (PMID 30266084, 2018). "Moreover, they observed the positive correlation between EED overexpression and the aggressiveness of the clinicopathological features of patients with colorectal cancer, such as facilitated lymph node metastasis, distal metastasis and lower disease-free survival." (PMID 33882457, 2021). "Analysis of larger colorectal cancer datasets further revealed consistent upregulation of EZH2, EED, and UHRF1 in BRAF-mutant CRCs compared to BRAF-wildtype tumors, reinforcing the broader relevance of these findings." (PMID 40678543, 2025). "Besides, through analyzing colorectal cancer RNA sequencing data in TCGA, we found SNHG1 expression was positively correlated with EZH2, SUZ12 and EED." (PMID 30266084, 2018).
gastric cancer (3 papers, 2021 to 2023). A primary or metastatic malignant neoplasm involving the stomach. "In addition, in gastric cancer, embryonic ectoderm development protein (EED) can suppress the expression of miR-338-5p by promoting histone methylation." (PMID 37781524, 2023).
Intellectual Disability syndromes (3 papers, 2019 to 2025). "In line with this, a group of related human developmental overgrowth syndromes, including the Weaver, Weaver-like, Cohen-Gibson, and Overgrowth and Intellectual Disability syndromes, appear to be caused by heterozygous mutations in EED, EZH2 or SUZ12." (PMID 35245348, 2022). "In line with this notion, several related human developmental syndromes, including the Weaver, Weaver-like, Cohen-Gibson, and Overgrowth and Intellectual Disability syndromes, have been linked to heterozygous, usually de novo, mutations in EED, EZH2, or SUZ12." (PMID 30807568, 2019). "Furthermore, this approach can accurately classify variants of uncertain significance in EED and SUZ12, thereby identifying pathogenic variants in individuals with undiagnosed overgrowth/intellectual disability syndromes." (PMID 40922349, 2025).
medulloblastoma (3 papers, 2018 to 2023). A malignant, invasive embryonal neoplasm arising from the cerebellum. "We show that Polycomb Repressive Complex-2 (PRC2) components EED and EZH2 maintain neural identity in cerebellar granule neuron progenitors (CGNPs) and SHH-driven medulloblastoma, a cancer of CGNPs." (PMID 36635771, 2023). "During cerebellum development and medulloblastoma progression, RNF220 promotes Shh signaling epigenetically through targeting EED for degradation, overwriting its effects on Gli ubiquitination." (PMID 32630355, 2020). "In cerebellar granule neuron progenitors and medulloblastoma cells, RNF220 targets EED for degradation and promotes Shh signaling epigenetically." (PMID 32630355, 2020). "Multiple other genes belonging to PRC1 and PRC2 complexes, including BMI1, EED and SUZ12 have been found upregulated either in specific medulloblastoma subgroups or across medulloblastoma generally." (PMID 29759978, 2018). "Our data show that CGNPs and medulloblastoma cells require PRC2 to maintain neural fate commitment, and that EED is specifically required for cerebellar growth, but neither EED nor EZH2 are required for medulloblastoma progression." (PMID 36635771, 2023).
prostate carcinoma (3 papers, 2021 to 2025). A carcinoma that arises from epithelial cells of the prostate gland. "Previous studies using the VCaP prostate cancer cell linehave shown that HOXB13 precipitates with the EED protein,which is a component of the PRC2 repressor complex (Cao etal., 2014)." (PMID 41164275, 2025). "In accordance with tissue origin data, the majority of alterations in the EZH2, SUZ12, and EED genes in prostate cancer are represented by amplifications." (PMID 34202528, 2021). "EZH2, SUZ12, and EED gene amplification was most frequently found in prostate cancer, whereas lymphoid malignancies (DLBCL) frequently showed EZH2 mutations." (PMID 34202528, 2021). "Here, we show that amplification and higher expression of EZH2 and EED correlate with poor survival, further supporting the involvement of EZH2 and its PRC2 protein partners in prostate cancer." (PMID 34202528, 2021).
T-cell acute lymphoblastic leukemia (3 papers, 2020 to 2023). Acute lymphoblastic leukemia of T-cell origin. "Loss-of-function mutations in EZH2, EED, or SUZ12 occur in a subset of myeloid malignancies, T-cell acute lymphoblastic leukemia (T-ALL), and malignant peripheral nerve sheath tumors (MPNSTs)." (PMID 37051671, 2023).
Alzheimer disease (2 papers, 2022 to 2025). A progressive, neurodegenerative disease characterized by loss of function and death of nerve cells in several areas of the brain leading to loss of cognitive function such as memory and language. "One locus overlapped with a known Alzheimer's disease GWAS locus (EED/PICALM) and 2 with GWAS loci for circulating ω-3 fatty acids (SRSF4 and PSMG1)." (PMID 40949174, 2025). "From the comparison of FOS exclusively defined by two questionnaires, interaction signals around peroxisomal biogenesis factor 26 (PEX26), EED, and CAMK2D were replicated in all-cause dementia, Alzheimer's disease, and vascular dementia outcomes, respectively." (PMID 40949174, 2025). "However, using an extended and even more recent list of GWAS results from the European Alzheimer’s disease DNA biobank (EADB) project published as preprint reveals several new connections, i.e. for ADAM17 & USP6NL (both miR-129-5p), CTSB & EED (miR-138-5p), and ANK3 & PLEKHA1 (miR-195-5p)." (PMID 36038535, 2022).
bladder cancer (2 papers, 2022 to 2025). "In human bladder cancer, gene sets associated with H3K27me3 and PRC2 (SUZ12/EED) targets were also positively enriched in KMT2C/D mutant samples." (PMID 39806204, 2025). "In literature, correlation between elevated EZH2, SUZ12 and/or EED gene expression and poor prognosis of bladder carcinoma were reported." (PMID 36428492, 2022).
dilated cardiomyopathy (2 papers, 2017 to 2024). Cardiomyopathy which is characterized by dilation and contractile dysfunction of the left and right ventricles. "EED (embryonic ectoderm development) inactivation in the postnatal heart (EedCKO) caused lethal dilated cardiomyopathy." (PMID 28394251, 2017).
endometriosis (2 papers, 2017 to 2021). The growth of functional endometrial tissue in anatomic sites outside the uterine body. "When compared to the EuN tissues, expression of all three PRC2 protein complex (SUZ12, EED and EZH2) and JARID2, was higher in both the eutopic (EuE) and ectopic (EcE) tissue from endometriosis patients." (PMID 33800594, 2021). "DZNep also significantly abrogated the expression of EZH2, EED, SUZ12, H3K9me3 and H3K27me3 in eutopic/control endometrial epithelial cells from mice with or without induced endometriosis, all in a dose-dependent manner." (PMID 28754964, 2017). "qPCR was used to determine the mRNA expression of PRC2 components SUZ12, EED, and EZH2 in eutopic tissue from women with no endometriosis (EuN, n = 5) or women with endometriosis (EuE, n = 10) and ectopic tissue from women with endometriosis (EcE, n = 6)." (PMID 33800594, 2021).
heart failure (2 papers, 2017 to 2023). Inability of the heart to pump blood at an adequate rate to meet tissue metabolic requirements. "EED also interacts with the neutral sphingomyelinase 2, which is involved in inflammation, heart failure, AS, and other biological processes." (PMID 36969166, 2023). "Interestingly, delayed EED re-expression was still able to rescue cardiac systolic function and cardiac hypertrophy, normalize expression of myofiber and heart failure genes, and ameliorate cardiomegaly of EedCKO mutants." (PMID 28394251, 2017).
psoriasis (2 papers, 2018 to 2025). An autoimmune condition characterized by red, well-delineated plaques with silvery scales that are usually on the extensor surfaces and scalp. "Our analysis showed differential expression of EED, EZH1/2, and RBBP4 in the PRC2 complex, likely to affect stem cell self-renewal and possibly contributing to keratinocyte hyperproliferation in psoriasis." (PMID 40650108, 2025).
acute kidney injury (1 paper, 2022). Sudden and sustained deterioration of the kidney function characterized by decreased glomerular filtration rate, increased serum creatinine or oliguria. "In this study, we investigated the role and underlying mechanism of the PRC2 in acute kidney injury (AKI) by using EED226, a highly selective PRC2 inhibitor, to target EED." (PMID 35734954, 2022).
adenoma (1 paper, 2013). A neoplasm arising from the epithelium. "Furthermore, our gene expression data show that PRC2 components are over-expressed in adenoma, and immunohistochemistry confirmed up-regulation of EED protein in adenoma tissue." (PMID 23408899, 2013). "In addition, immunohistochemical analysis on sections of normal and adenoma tissue found up-regulation of EED and DNMT1 protein in adenoma." (PMID 23408899, 2013).
Autoimmunity (1 paper, 2021). The occurrence of an immune reaction against the organism's own cells or tissues. "Because peripheral Treg cannot compensate for AIRE deficiency, the absence of autoimmunity corroborated our finding that EED deficiency results only in a minor alteration of TRA representation." (PMID 34168132, 2021).
breast tumors (1 paper, 2025). "All PRC2 components, except for EED and EZH1, were significantly enriched in breast tumors compared to normal tissues." (PMID 41413688, 2025).
Cerebral ischemia (1 paper, 2013). Restriction of arterial blood supply to the brain associated with insufficient oxygenation to support the metabolic requirements of the tissue. "In the present study, coimmunoprecipitation data suggest that cerebral ischemia induced the increased binding of nSMase2 with RACK1 and EED, which might have been associated with nSMase2 activation in the early phase of ischemia." (PMID 24007266, 2013). "Although enhanced binding of nSMase2 with RACK1 and EED were also observed after cerebral ischemia, nSMase2 activity was not blocked by the TNF-α receptor inhibitor through RACK1/EED signaling." (PMID 24007266, 2013).
chronic myelogenous leukemia (1 paper, 2023). "We next determined the effect of these compounds on reducing the protein levels of BMI1, RING1B, EED, and H2AK119ub in K562 cells, a chronic myelogenous leukemia cell line." (PMID 36737841, 2023).
developmental delay (1 paper, 2024). "Consistent with previous studies, later development of offspring generated from oocytes lacking EED was characterised by developmental delay of the fetus and placental hyperplasia." (PMID 38813868, 2024).
diffuse intrinsic pontine glioma (1 paper, 2023). A neuroglial tumor that arises from the middle portion of the brain stem. "A knockout screen on tumour sphere cells derived from diffuse intrinsic pontine glioma also ranked knockout of UBE2N, CHD4 and EED as a hit in combination with the histone deacetylase inhibitor panobinostat." (PMID 37161535, 2023).
Ewing tumors (1 paper, 2016). "Our results were in agree with Burdach and colleagues that demonstrated loss of regulation of both EED and SUZ12 expression in Ewing tumors." (PMID 27471434, 2016).
follicular lymphoma (1 paper, 2022). Follicular lymphoma is a form of non-Hodgkin lymphoma characterized by a proliferation of B cells whose nodular structure of follicular architecture is preserved. "Recently, analogs of EED226 (e.g., EEDi-5285) have been further developed and optimized with an enhanced binding affinity for EED and the ability to inhibit growth in mouse xenograft models of human follicular lymphoma." (PMID 36105358, 2022). "Also, small-molecule compounds that interfere with the EED/EZH2 interaction have been developed (e.g., astemizole and DC-PRC2in-01) and tested in PRC2-dependent follicular lymphomas." (PMID 36105358, 2022).
glioblastoma (1 paper, 2020). The most malignant astrocytic tumor (WHO grade IV). "Intriguingly, Trametinib appeared to specifically reduce ZNF263 protein levels without altering those of KAP1, SUV39H2, EED, or SETDB1, implying that the activation of EGFR/MAPK led to SIX3 silencing in glioblastoma mainly through the regulation of ZNF263." (PMID 32051553, 2020).
ischemia (1 paper, 2013). A hypoperfusion of the BLOOD through an organ or tissue caused by a PATHOLOGIC CONSTRICTION or obstruction of its BLOOD VESSELS, or an absence of BLOOD CIRCULATION. "However, the inhibition of TNF-αR attenuated the nSMase2 activity to some extent, suggesting that the TNF-αR/RACK1/EED pathway plays a secondary role in the upregulation of nSMase2 activity in hippocampal astrocytes following ischemia." (PMID 24007266, 2013).
leiomyoma (1 paper, 2018). A well-circumscribed benign smooth muscle neoplasm characterized by the presence of spindle cells with cigar-shaped nuclei, interlacing fascicles, and a whorled pattern. "SUZ12 and EED protein expression in LMS was deceased comparing with leiomyoma and myometrium." (PMID 30120321, 2018).
leiomyosarcoma (1 paper, 2019). An uncommon, aggressive malignant smooth muscle neoplasm, usually occurring in post-menopausal women. "These tumors lacked PRC2 (EED, SUZ12) mutations, and no mutations were present in RBL2 or SP100, two altered telomere maintenance genes found to be enriched in ALT-positive leiomyosarcomas." (PMID 31462295, 2019).
liver cancer (1 paper, 2010). An epithelial or non-epithelial malignant neoplasm that arises from the liver. "MiR-101 targets two subunits of PRC2 complex, enhancer of zeste homolog 2 (EZH2) and EED, and was shown to play as a tumor suppressor gene in human prostate, breast and liver cancers." (PMID 20444294, 2010).
melanoma (1 paper, 2022). A malignant, usually aggressive tumor composed of atypical, neoplastic melanocytes. "Human melanoma patients with decreased EED or SUZ12 mRNA have decreased overall survival." (PMID 35223844, 2022). "Melanoma cases were found to contain homozygous and heterozygous deletions in EZH2, SUZ12, and EED, and cases with these alterations frequently had decreased mRNA levels of the deleted gene." (PMID 35223844, 2022). "We identified a proportion of melanoma cases which harbored chromosomal amplifications and gains of regions including EZH2, SUZ12, and EED." (PMID 35223844, 2022).
NK T cell lymphoma (1 paper, 2018). "Coactivation of PRC2 proteins (EZH2, SUZ12, and EED) were reported to be associated with inferior OS in NK T cell lymphoma." (PMID 29415665, 2018).
osteoarthritis (1 paper, 2022). A noninflammatory degenerative joint disease occurring chiefly in older persons, characterized by degeneration of the articular cartilage, hypertrophy of bone at the margins and changes in the synovial membrane. "However, there are few studies on the roles of EED in osteoarthritis and immunity, hence exploring the epigenetic mechanisms mediated by EED in OA immune infiltration may be a novel strategy to improve the immune microenvironment of OA." (PMID 36550476, 2022).
ovarian carcinoma (1 paper, 2021). A malignant neoplasm originating from the surface ovarian epithelium. "The ovarian, skin, prostate and soft tissue tumors are characterized by over 1% amplification frequency of EZH2 and EED genes with the highest frequency in ovarian cancer: 11.4% and 9.84%, respectively." (PMID 34202528, 2021).
prostate adenocarcinoma (1 paper, 2021). "The strongest correlation between high mRNA abundance and poor survival was observed for EZH2 and EED in prostate adenocarcinoma (logrank p < 0.01; hazard ratio 6.52 and 5.16, respectively)." (PMID 34202528, 2021). "Here we demonstrated that along with prostate adenocarcinoma, other tumor types show a correlation between high EZH2, SUZ12 and EED levels and a shorter survival, suggesting that these cancers could be potential targets for EZH2/SUZ12/EED inhibitor therapy." (PMID 34202528, 2021).
prostate neuroendocrine carcinoma (1 paper, 2021). "Detailed analysis of tumor subtypes identified CRPC and prostate neuroendocrine carcinoma as the tumors with the highest amplification rate (12–23%) of EZH2, SUZ12 and EED genes." (PMID 34202528, 2021).
renal clear cell carcinoma (1 paper, 2021). "In renal clear cell carcinoma, higher expression of EZH2 and EED was significantly correlated with poor prognosis, whereas high levels of SUZ12 were associated with longer survival." (PMID 34202528, 2021).
soft tissue tumors (1 paper, 2021). "Similar tendency for the higher rate of EZH2 and EED amplification was found for skin, prostate, and soft tissue tumors." (PMID 34202528, 2021).
spinocerebellar ataxias (1 paper, 2024). "Interestingly, Kyoto Encyclopedia of Genes and Genomes (KEGG) analysis of genes downregulated upon loss of EED revealed neuronal functions and spinocerebellar ataxias are the most enriched biological processes." (PMID 39498824, 2024).
thyroid cancer (1 paper, 2023). "To determine whether EZH2/PRC2 components are deregulated in PTC and ATC, we first analyzed the expression of EZH2, EED and SUZ12 in BRAFV600E thyroid cancer cell lines." (PMID 37175580, 2023).
uterine corpus endometrial carcinoma (1 paper, 2021). A endometrial carcinoma (disease) that involves the body of uterus. "For the uterine corpus endometrial carcinoma, high expression of EZH2 was correlated with poor survival, although higher expression of EED was associated with a longer survival." (PMID 34202528, 2021).
Uterine leiomyoma (1 paper, 2018). The presence of a leiomyoma of the uterus. "SUZ12 and EED protein were detected in 18 of 32 (56.25%) and 14 of 32 (43.75%) LMS, respectively, and they were lower than that in uterine leiomyoma (16/16,100%) and normal myometrium (16/16,100%) (p < 0.05)." (PMID 30120321, 2018).
uveal melanoma (1 paper, 2022). A melanoma derived from melanocytes of the uveal tract. "To investigate the importance of EZH2 in uveal melanoma cells, we examined several small-molecule methyltransferase inhibitors, including UNC 1999, EPZ6438, GSK126, and GSK503, and the embryonic ectoderm development protein (EED) inhibitor EED226 in OMM1 cells." (PMID 36276954, 2022).
viral infection (1 paper, 2018). "A moderate antiviral activity is associated with EED isoform EED-3 and EED-4 in the early phase of infection, while a strong negative effect on HIV-1 replication has been observed at late phase of viral infection." (PMID 29441145, 2018).